CCL2 (C-C motif chemokine ligand 2)
Diseases named in the same sentence as CCL2 in open-access papers (continued):
Sharing a sentence is not in itself a finding about the gene and the disease.
periodontal disease (19 papers, 2010 to 2025). "Given the established association of CCL2 polymorphism with periodontal disease, we further confirmed the frequency of CCL2 polymorphism in our sample using PCR." (PMID 37927745, 2023). "Consequently, the pathological degradation of the extracellular matrix associated with periodontal disease is related to CCL2 production and activation." (PMID 37927745, 2023). "We focused on the measurements on the expression of IL-6, CXCL8, and CCL2, which are thought to play an important role in the progression of periodontal disease." (PMID 27504628, 2016). "Another chemokine that could contribute to the enhanced severity of periodontal disease is macrophage chemoattractant protein-1 (MCP-1/CCL2), which is supposed to be the major chemoattractant of macrophages in periodontal diseases." (PMID 24151615, 2013). "TNFα (p = 0.0038), MCP1 (CCL2) (p = 0.0493), IL-1β (P = 0.0043), and IL-8 (p = 0.0035) were increased in OSCC compared to control only while MIP1β (CCL4) (p < 0.0365) was increased in OSCC patients compared to periodontal disease patients." (PMID 35048057, 2021).
Cachexia (18 papers, 2014 to 2026). Severe weight loss, wasting of muscle, loss of appetite, and general debility related to a chronic disease. "The sarcopenia and cachexia causing the skeletal muscle loss in the genetically modified mice were significantly altered by Ccl2 overexpression." (PMID 33104522, 2020). "To test if appetite suppression by CCL2 was responsible for lethal cachexia we performed single nucleus RNA sequencing of the hypothalamus, the center of appetite control in the brain." (PMID 40060612, 2025). "Consistent with prior studies, KxPxCx allograft-induced cachexia resulted in hypothalamic inflammation in vehicle-treated animals, with increases in expression of Selp, Il1b, Il1r1, Tlr7, Ccl2, and Icam1." (PMID 31615993, 2019). "In the present study, we found a linear increase in the CD68+ myeloid population, paralleling the progression of cachexia, which was endorsed by the finding of increased detection of specific receptors (F4/80 and Cd68) and chemokine (Ccl2) genes of CD68+ population." (PMID 37177862, 2023). "Our cachexia classification was validated by the increase of CIFs genes in the tumor of LM patients, such as LIF, IL6, IFNG, and CCL2." (PMID 36774484, 2023). "Interestingly, CCL2 treatment did not affect ATP production, a phenotype observed in some models of cancer cachexia but not in others." (PMID 38973385, 2024).
cerebral infarction (18 papers, 2011 to 2025). An ischemic condition of the brain, producing a persistent focal neurological deficit in the area of distribution of the cerebral arteries. "In support of this notion, CCL2 deficiency results in less infiltration of immune cells, smaller brain infarction, and reduced BBB leakage in MCAO mice." (PMID 35185544, 2021). "Multiple logistic regression analysis revealed that MCP-1/CCL2 levels were significantly associated with the presence of silent cerebral infarction in this population." (PMID 31474869, 2019). "Meanwhile, although we have demonstrated the significance of IL-17A, we also observed reduced levels of IL-1β and CCL2 in the cerebral infarction homogenates of P2X7-KO mice following tMCAO." (PMID 40948793, 2025). "Further, studies have demonstrated that the genetic deletion of CCL2 and CCR2 reduced the permeability of the BBB, the accumulation of immune cells in ischemic brain tissues, and subsequent cerebral infarction." (PMID 32872405, 2020). "Furthermore, studies have shown that genetic deletion of CCL2 and CCR2 reduces BBB permeability, accumulation of immune cells in ischemic brain tissue, and subsequent cerebral infarction." (PMID 35493318, 2022).
dermatitis (18 papers, 2015 to 2026). An inflammatory process affecting the skin. "Specifically, we observed attenuation of skin inflammation and a significant reduction in expression of mast cell mediators such as CCL2, IL-6, TNFα and MMP9 in the presence of osthole." (PMID 32391014, 2020). "To test the importance of several of these molecules in TWEAK-mediated skin inflammation, we blocked CCL2, CCL5 and CCL7 together, by injecting neutralizing antibodies at the time of rTWEAK injection." (PMID 28530223, 2017). "In addition, bentonite pre-treatment markedly suppressed the secretion of IL-6, IL-8, and CCL2, key mediators of skin inflammation, in keratinocyte cultures (p < 0.05 for all comparisons)." (PMID 41576001, 2026). "Additionally, IL-31 is activated when the IL-31Rα receptor chain in primary human CD1c+ and monocyte-derived DCs is upregulated by IFN-γ stimulation, leading to a dose-dependent release of inflammatory mediators such as TNF-α, IL-6, CXCL8, CCL2, CCL5, and CCL22, causing skin inflammation." (PMID 38590314, 2024). "Although IL-31 activates STAT-3 phosphorylation and enhances C-C motif chemokine 2 (CCL2) secretion in human primary keratinocytes, this phenomenon is not observed in AD keratinocytes with low TLR-2 expression, suggesting a potential link between the functional change of IL-31 and skin inflammation." (PMID 38590314, 2024).
diabetic macular edema (18 papers, 2011 to 2025). "In both mice and humans, BRB disruption is associated with a more advanced DR stage, and CCL2 levels are increased in patients with DR and correlate with diabetic macular edema, a marked cause of vision loss in patients with DR." (PMID 39207852, 2024). "Thus, CCL2 may be an important therapeutic target for the treatment of diabetic macular edema." (PMID 25329075, 2014).
emphysema (18 papers, 2011 to 2025). "The mechanism of the emphysema is complex, and matrix metalloproteinases, particularly MMP-9 and MMP-12, are of interest; activation of the IL-17 → MCP-1(Ccl-2) → MMP-9 → MMP-12 axis appears to be critical for the formation of emphysema." (PMID 38892239, 2024). "The central role of CCL2 and CCL7, and thus MoAM, in lung inflammation and pathology is corroborated by a strongly impaired recruitment of monocytes into the lung and protection from pulmonary emphysema upon inhibition of the CCR2/CCL2 axis." (PMID 38348034, 2024). "In mice, IL-17 is essential for the development of emphysema from long term CS exposure by activating the IL-17 → Ccl-2 → MMP-9 → MMP-12 signaling axis." (PMID 27363862, 2016). "In vivo cigarette smoke induces CCL2 in the lung in an IL-17RA dependent manner, and IL-17RA is essential for smoke induced macrophage recruitment and emphysema." (PMID 21647421, 2011). "Taken together these data demonstrate that cigarette smoke is a potent Th17 adjuvant and that IL-17RA signaling is required for the elaboration of CCL2, macrophage recruitment and tissue emphysema." (PMID 21647421, 2011). "Taken together, these data suggest that IL-17RA expression may be affecting two independent processes that are required for the development of emphysema, namely macrophage recruitment via CCL2 and induction of MMP12 by CXCL10." (PMID 21647421, 2011). "Given the fact that IL-17 over expression increases CCL2 expression, we hypothesized that IL-17RA−/− mice would have reduced macrophage recruitment and reduced cigarette smoke induced emphysema." (PMID 21647421, 2011). "A higher IL-17 expression correlates with higher MMP-12 mRNA expression, which plays a significant role in the formation of emphysema; a stimulation of the IL-17 → MCP-1(Ccl-2) → MMP-9 → MMP-12 axis is crucial." (PMID 36293561, 2022). "After 6 months of cigarette smoke exposure we found that IL-17RA was critical for the induction of CCL2, macrophage recruitment, MMP12 expression, and emphysema in mice." (PMID 21647421, 2011). "Interestingly, the intratracheal administration of CCL2 can augment emphysema but not in MMP12−/− mice, suggesting that MMP12 rather than macrophages per se is critical for emphysema." (PMID 21647421, 2011). "Moreover, CS-exposed IL-17RA−/− mice failed to induce CCL2 (MCP1) and MMP12 and did not develop emphysema after 6 months of exposure." (PMID 26284585, 2016).
ovarian tumor (18 papers, 2005 to 2025). "The chemokine CCL2 is the major determinant of monocyte recruitment at tumor sites, whereas IL-6 is a growth factor for ovarian tumors." (PMID 40007535, 2025). "To further investigate the extent and localisation of CCL2 expression in primary ovarian tumours, we used mRNA ISH to analyse two normal ovaries and 13 primary adenocarcinomas." (PMID 15900302, 2005). "CCL2 (MCP-1) is an important determinant of macrophage infiltration in ovarian tumors." (PMID 25790431, 2015). "It has also been reported that CCL2/MCP-1 is increased after paclitaxel–carboplatin combination treatment, resulting in macrophage recruitment into ovarian tumors and inhibition of CCL2/MCP-1 increases response to chemotherapy." (PMID 39287565, 2024). "Several inflammatory molecules, including RANTES/CCL5, MCP-1/CCL2, and IL-6 were upregulated after transfection of murine ovarian tumor cells O/N with poly (I:C) (10 μg/ml), compared to the untreated cell supernatants." (PMID 30613350, 2018). "Ovarian tumors recruit circulating monocytes and induce differentiation into TAMs via expression of factors such as CCL2, also known as monocyte chemotactic protein-1 (MCP-1), and macrophage colony stimulating factor-1 (M-CSF or CSF-1)." (PMID 24936477, 2014). "In ovarian tumors, functional activity for TLR4 was demonstrated by stimulation of cell lines with specific ligands and subsequent activation and translocation of NF-κB and release of the proinflammatory cytokines interleukin-6 and CCL-2." (PMID 22985132, 2012). "CCL2 is overexpressed in ovarian tumor cells and cell lines, but not in TAMs." (PMID 24936477, 2014).
prostate tumor (18 papers, 2010 to 2025). "This highlights a vital cross-talk between tumor cells and the immune stroma: CCL2 secretion inhibits starvation-induced apoptosis of tumor-associated macrophages (TAMs) and acts as a potent chemoattractant, significantly increasing macrophage infiltration into prostate tumors in vivo." (PMID 41162970, 2025). "Previous studies have shown that certain inflammatory factors (such as CCL2) can promote prostate tumor growth and bone metastasis by recruiting macrophages." (PMID 33859877, 2021). "High levels of CCR2 exist in prostate tumor cell surface to respond to autocrine and/or paracrine CCL2 in the microenvironment." (PMID 32471499, 2020). "Consistently, immunohistochemical (IHC) staining confirmed increased CCL2 expression in MARKO/TRAMP prostate tumours with increased numbers of F4/80 positive macrophages." (PMID 23982944, 2013). "Human prostate tumors as well as well as primary prostate epithelial cells (PrEC) are known to secrete the chemokine CCL2 (MCP-1)." (PMID 20593019, 2010). "CCL2 was overexpressed in primary prostatic tumors as determined by immunohistochemistry." (PMID 32471499, 2020). "Human and murine prostate tumors have been previously reported to express CCL2, CCL5 and CXCL12." (PMID 27177227, 2016). "In a prostate tumor xenograft model of mice implanted with LNCaP cells, HFD promoted tumor growth and increased blood CCL2 levels." (PMID 32471499, 2020). "We then examined CCL2 expression in the prostate tumour of pesARKO/TRAMP mice, and found increased CCL2 expression." (PMID 23982944, 2013). "Collectively, these data indicate the CCL2:CCR5-mediated iNKT cell attraction by prostate tumor cells and strongly suggest that CCR5 and CCL2 play critical roles in iNKT cell migration into prostate tumors." (PMID 20593019, 2010). "In our dataset, we observed high expression of CXCL12 in fibroblasts, CCL2 in pericytes, and CCL3,4, and 5 in epithelial and tumor cells, suggesting a potential role of fibroblasts and pericytes in recruiting monocytes to the prostate tumor." (PMID 36750562, 2023). "CCL2 and CCL5 are closely related to prostate tumor metastasis and tumor resistance." (PMID 34367971, 2021). "Furthermore, other cytokines such as CCL2, RANKL, IL-6, CXCL8, and IL-1 are known to drive osteoclastogenesis and bone resorption: key events observed following prostate tumor metastasis to the bone." (PMID 32585812, 2020). "We first tested whether mouse prostate tumors and the derived cell line TRAMP-C2 secrete CCL2." (PMID 20593019, 2010). "The results demonstrate that despite being expressed in prostate tumours, CCR2 and CCL2 have no prognostic value in the disease." (PMID 39199567, 2024).
anaphylaxis (17 papers, 2011 to 2025). An acute hypersensitivity reaction that occurs from exposure to an allergen. "Further in vitro experiments revealed that the serum from patients with acute phase anaphylaxis promoted basophil chemotaxis in a CCL2-depedent manner, suggesting the role of CCL2-mediated basophil chemotaxis during systemic anaphylaxis." (PMID 35693800, 2022). "A recent study comparing baseline and reaction samples in perioperative anaphylaxis revealed IL-6 and CCL2 as potential biomarkers." (PMID 34575019, 2021). "Our findings imply an important and specific role for CCL2 in the pathophysiology of human anaphylaxis." (PMID 33317619, 2020). "Our findings imply an important and specific role for CCL2-mediated chemotactic activity in the pathophysiology of human anaphylaxis." (PMID 33317619, 2020). "This study not only highlights the use of CCL-2 as a biomarker for anaphylaxis, but also suggests CCL-2 levels in acute serum correlate with the severity of the reaction." (PMID 31024519, 2019). "The study also found the concentration of CCL-2 to be significantly higher in anaphylaxis, compared to both the samples taken in convalescence and in the healthy control cohort." (PMID 31024519, 2019). "Our data suggest a substantial migration of circulating basophils during anaphylaxis, which correlates with a significant increase in serum concentrations of the major basophil chemotactic factor CCL2." (PMID 28342911, 2017). "Basophil migration might be mediated by the chemokine CCL2, levels of which are increased during anaphylaxis and which can induce selective migration of human basophils." (PMID 36569939, 2022). "CCL2 serum levels may correlate with the severity of anaphylaxis, but glycosylation influences its chemotactic potency." (PMID 34575019, 2021). "Interestingly, during anaphylaxis (in an ED experimental set‐up), only an increase in CCL2 was observed, and increases of this chemokine significantly correlated with a decrease in circulating basophils." (PMID 29431885, 2018). "For example, many dogs with anaphylaxis showed increased plasma IL-10 concentration, known to increase within an hour of shock or endotoxaemia, and some dogs showed elevated plasma IL-6 or CCL2, known to increase within 1–3 h of shock, endotoxaemia or surgical stimulus." (PMID 36003410, 2022). "Therefore, it is tempting to speculate that the blood CCL2 increase that occurs during anaphylaxis is IgE related and mainly mast cell derived." (PMID 33317619, 2020). "Both IL-10 and CCL2 concentrations were significantly higher in the anaphylaxis group (IL10 P < 0.0001, CCL2 P = 0.007) and the critical illness group (IL10 P = 0.007, CCL2 P < 0.001), compared to the healthy group." (PMID 36003410, 2022). "The major basophil chemotactic factor, chemokine (C-C motif) ligand 2 (CCL2), was also examined as a biomarker in anaphylaxis, but only preliminary data are published." (PMID 34575019, 2021). "There is growing evidence to support the investigation of other biomarkers, such as chymase, carboxypeptidase A3, dipeptidyl peptidase I (DPPI), basogranulin, CCL-2, and platelet activating factor (PAF) in the diagnosis of anaphylaxis." (PMID 31024519, 2019). "There has been an interest in the detection of newer biomarkers in anaphylaxis including platelet activation factor (PAF), chymase, carboxypeptidase A3, dipeptidyl peptidase I (DPPI), basogranulin, and CCL-2." (PMID 31024519, 2019). "Using paired baseline measurements of CCL-2, they also showed a significantly higher increase of CCL-2 in patients with grade IV anaphylaxis compared to those with grade I reaction." (PMID 31024519, 2019). "A recent study demonstrated an increase in CCL2 (C-C Motif Chemokine Ligand 2) levels during human anaphylaxis, with no changes demonstrated for the chemokines CCL5 and CCL11." (PMID 33317619, 2020).
anaphylaxis (continued). "CCL2 levels (but not those of other serum markers) were significantly higher during anaphylaxis (median, 658 pg/mL) than in convalescent samples (314 and 311 pg/mL at 7 and 30 days, P < .001)." (PMID 28342911, 2017). "Although CCL2 displays major chemotactic activity for monocytes and interferes with the egress of monocytes from the bone marrow to the circulation during homeostasis and inflammation, no changes in circulating monocytes were observed during anaphylaxis." (PMID 33317619, 2020). "The potential use of CCL-2 as a biomarker in anaphylaxis was examined by one group, who measured CCL-2 at 3 time points (during the anaphylactic episode and in convalescent samples 7 and 30 days later) in 31 patients presenting to the emergency department with anaphylaxis." (PMID 31024519, 2019). "In the present study, we could not determine the cellular sources of CCL2 during anaphylaxis." (PMID 33317619, 2020).
astrocytoma (17 papers, 2005 to 2024). "A human astrocytoma cell line (U87-MG) was activated with IL-1β and transfected with firefly luciferase constructs containing a 929 bp fragment representing the distal CCL2 promoter with either the -2578 A allele or the -2578 G allele." (PMID 21760952, 2011). "Consistent with increased mRNA levels, CCL2 protein concentration was increased in high-grade astrocytoma (142.2 ± 47 pg/mL) compared to normal brain (5.7 ± 3 pg/mL; **P < .01)." (PMID 34131649, 2021). "Given the recent observation of the abundance of CD4+ cells in canine astrocytoma, further evaluation of the source and specific role(s) of CCL2 in canine astrocytoma is warranted." (PMID 34131649, 2021). "CCL2 mRNA was increased 59-fold in canine high-grade astrocytoma tumor homogenates compared to normal canine brain (**P < .01)." (PMID 34131649, 2021). "Conversely, infection of this same astrocytoma cell line by T. cruzi down-modulated the expression of CCL2/JE/MCP-1, a CC-chemokine shown to control T. cruzi growth in primary cultures of macrophages and cardiomyocytes." (PMID 25695249, 2015). "Chemokine ligand 2 (CCL2) is one of several cytokine genes and could be secreted by astrocytoma cells and myeloid cells." (PMID 32296458, 2020).
Autoimmunity (17 papers, 2008 to 2025). The occurrence of an immune reaction against the organism's own cells or tissues. "While the full‐length CCL2 binds to its receptor CCR2, which is expressed by activated Th1, Th17 and NK cells, and recruits them into the inflammation sites, the truncated CCL2 plays a critical role in the autoimmunity suppression by MSCs." (PMID 31730279, 2020). "Similarly, Irgm1−/− mice exhibit elevated type I IFN and CCL2, consistent with features of type I interferonopathy and autoimmunity." (PMID 40607809, 2025). "CCL2 (MCP-1) and its main receptor CCR2 have been widely studied and linked to a host of inflammatory responses including infection, cardiovascular disease, neuro-inflammatory and degenerative disease, autoimmunity, and cancer." (PMID 30671055, 2018).